INS (insulin)
Diseases named in the same sentence as INS in open-access papers (continued):
Sharing a sentence is not in itself a finding about the gene and the disease.
Insulin resistance (continued). "The results of this study showed that, resveratrol supplementation increased blood insulin level, reduced the fasting blood glucose, and improved the insulin resistance." (PMID 25999625, 2015). "This indicates that reduced insulin clearance is a compensatory mechanism that allows the organism to overcome insulin resistance, which attenuates the beta cell overload and increases their survival, thus delaying and/or ameliorating type 2 diabetes." (PMID 25822220, 2015). "The gene expression data from this study showed that the HFD + SIM and HFD groups had transcriptional changes of insulin signaling genes that tended towards insulin resistance." (PMID 26688813, 2015). "Insulin resistance is defined as a clinical state in which insulin-responsive tissues (including liver, muscle and adipose tissue) are insensitive to normal or elevated insulin levels and subsequently trigger a series of pathophysiological events." (PMID 26449763, 2015). "In this context, the present study aimed to evaluate if a 14-day oral GbE treatment alters retroperitoneal WAT depot insulin and Toll-like receptors signaling cascades of diet-induced obese rats, a model of insulin resistance." (PMID 25960614, 2015). "As examples, Cr supplementation has alleviated insulin resistance, enhanced intracellular insulin signaling in high fat diet/STZ rats, depressed lipolysis in adipocytes and inhibited gluconeogenesis in rats." (PMID 25652875, 2015). "Impaired insulin sensitivity and increased insulin resistance are profoundly involved in the pathogenesis and pathophysiology of type 2 DM and its associated cardiovascular complications." (PMID 25922845, 2015). "Here, we show that i.c.v.-injected AβOs induce peripheral glucose intolerance and hallmarks of insulin resistance, including adipose tissue inflammation and impaired insulin-induced surface translocation of GLUT-4 in skeletal muscle." (PMID 25617315, 2015). "In this study, as candidate genes we chose 1) genes related to T2DM, obesity, or insulin resistance found by previous GWAS and 2) genes related to glucose and lipid metabolism, insulin secretion, or MVCD, such as the HIF1α/-VEGF pathway." (PMID 26139146, 2015). "In contrast, elevated resistin has been proposed to increase insulin resistance, and the repression of resistin expression in normal mice by PPARγ agonists is thought to enhance insulin sensitivity." (PMID 25951943, 2015). "Degree of palmitate-induced insulin resistance was estimated by measuring changes in phosphorylation of insulin pathway proteins by western blotting as well as changes in expression of different type of transporters." (PMID 25635851, 2015). "Phenocopying global Ceacam1 null mice (Cc1–/–), C57/BL6J mice fed a high-fat (HF) diet exhibited reduced hepatic CEACAM1 levels and impaired insulin clearance, followed by hyperinsulinemia, insulin resistance, and visceral obesity." (PMID 26284027, 2015). "The role of HO-1 in T2DM and AD is further highlighted by the correlation between increased levels of HO-1 with brain oxidative markers and links with insulin resistance and insulin signalling." (PMID 26693205, 2015). "Administration of resveratrol improved insulin resistance as demonstrated by the reduced 86.2% insulin levels in this group in comparison to the MG group." (PMID 25884658, 2015). "These patients have significant hepatic insulin resistance, and the effects of insulin are impaired because of plasma free fatty acids (FFAs)." (PMID 26273677, 2015). "Obesity-related insulin resistance, however, affects not only adipose tissue but also all insulin target organs." (PMID 25759846, 2015). "Our data show that simvastatin induces insulin resistance in a cholesterol biosynthesis inhibition independent fashion but does so by a fatty acid mediated effect on insulin signaling pathway." (PMID 26345110, 2015).
Insulin resistance (continued). "While abnormal RAS activity and insulin resistance (such as impaired insulin effects on pre-adipocytes) can contribute to inflammatory changes, chronic inflammation by itself is also a causative factor in developing insulin resistance." (PMID 25714093, 2015). "Insulin-stimulated glucose uptake in skeletal muscle and adipocytes tissues is impaired in obesity and T2DM, causing peripheral insulin resistance (IR)." (PMID 25876175, 2015). "The present study found that β-amyloid deposition increased in the control group and exacerbated peripheral insulin resistance whereas MP and SP had fewer β-amyloid tangles and better peripheral insulin sensitivity." (PMID 25755673, 2015). "Requirement for short-term insulin therapy, increased body mass index and elevated basal glucose indicated that insulin resistance was the predominant feature of impaired glucose tolerance in GBS." (PMID 26684748, 2015). "It is well known that pancreatic beta cells respond to insulin resistance by increasing their cell mass (beta cell hyperplasia) and insulin secretion (hyperinsulinaemia)." (PMID 25912041, 2015). "Both can lead to mitochondrial dysfunction by compromising the ability to oxidize fat, resulting in interference with insulin signaling pathway and worsening the state of insulin resistance." (PMID 27417763, 2015). "Conversely, mice that overexpress Tcf7l2 display reciprocal phenotypes, including increased plasma insulin levels and glucose intolerance due to peripheral insulin resistance, indicating that overexpression of Tcf7l2 leads to a type 2 diabetic phenotype." (PMID 25398947, 2015). "We previously demonstrated that Ras/Src-activated cells preserve mitogenic effects of insulin under the systemic insulin resistance induced by HDS-feeding of Drosophila." (PMID 26573956, 2015). "In support of this, correlates of insulin resistance, insulin dose, and waist circumference were strongly related to adiponectin levels in adults at 20 years." (PMID 25950008, 2015). "Systemic insulin resistance and defective brain insulin signaling are common features of Alzheimer’s disease, thus rendering type 2 diabetes an important risk factor for this neurodegenerative disorder." (PMID 26023930, 2015). "Fasting insulin and insulin resistance as measured by HOMA-IR were nearly 50% lower in the PWS group than in controls." (PMID 26334732, 2015). "To confirm that an increased abundance of GM1 contributes to insulin resistance, we investigated insulin signaling in HAECs incubated with exogenous GM1." (PMID 26338710, 2015). "Insulin resistance and insulin sensitivity were evaluated by calculating the HOMA-IR and QUICKI indices." (PMID 26657014, 2015). "We recently demonstrated that AMPK activity in adipose tissues from bariatric surgery patients was significantly lower in individuals with insulin resistance than in subjects of comparable weight who were insulin sensitive." (PMID 25647160, 2015). "Studies evaluating the therapeutic effect of insulin sensitizing agents like MF on NAFLD should possibly take the patients' response regarding insulin resistance into account." (PMID 25873949, 2015). "A final novel facet of this study was the use of the lipoprotein-insulin resistance (LP-IR) score to quantify the relationship between dyslipidemia and insulin sensitivity." (PMID 26599819, 2015). "A progressive deterioration of glucose tolerance occurs with early β-cell compensation that is followed by a decrease in pancreatic β-cell mass with insulin resistance and impaired insulin secretion." (PMID 26064426, 2015). "This type of bariatric surgery is known to improve glucose tolerance, not only by reducing body weight and thus insulin resistance, but also by improving insulin secretion in response to glucose." (PMID 25723556, 2015). "Insulin is a key hormone that drives lipogenesis and hepatic steatosis is often accompanied by hepatic insulin resistance." (PMID 26067236, 2015).
Insulin resistance (continued). "Apart from insulin resistance, high triglyceride level is often measured in patients with persistent or inadequate insulin therapy." (PMID 26276522, 2015). "A marked hyperinsulinemia was also observed, since serum insulin levels were significantly elevated (more than twofold) above the control in rats with insulin resistance (p< 0.0001)." (PMID 25807378, 2015). "The degree of glucose intolerance and insulin resistance was more variable, as only half of the obese R1-miR19b animals showed impaired glucose tolerance and insulin sensitivity." (PMID 26658372, 2015). "Higher glucose, insulin and insulin resistance in childhood and a higher change in glucose–insulin between childhood and young adulthood were associated with higher CVD risk factors in early adulthood." (PMID 25940643, 2015). "Since leptin stimulates the transcription of genes encoding IR and IRS-proteins, a decrease of its regulatory effects at the early stages of insulin resistance leads to weakening of function of the brain insulin system and exacerbates insulin resistance." (PMID 28031898, 2015). "Diet-induced insulin resistance is mediated by several mechanisms, including the release of WAT-derived fatty acids and adipokines that blunt insulin signaling and cause ectopic lipotoxicity and a systemic pro-inflammatory state." (PMID 26045713, 2015). "Conceivably, increased preoperative insulin resistance leads to an adaptive increase of insulin secretion, which reverses after the removal of cholestasis and normalization of insulin resistance." (PMID 26248027, 2015). "Pathways: 6-27-47 and 7-26-44 in the integrated model show how catecholamines and glucocorticoids inhibit insulin actions and thus contribute to insulin resistance." (PMID 26231223, 2015). "AGEs impair the insulin signaling pathway, and previous studies demonstrated that food-derived MG-derivatives can contribute to insulin resistance in aged mice in quantities like they are found in standard diet." (PMID 25668621, 2015). "Insulin resistance is often present at the levels of all organs, muscle, liver, heart and adipose tissue, where insulin promotes FA esterification and synthesis of TAG." (PMID 26580649, 2015). "Fasting glucose, fasting insulin, homeostasis model analysis insulin resistance (HOMA-IR), blood lipids and apolipoprotein (Apo) B-100 (Apo B) and Apo A-I were determined." (PMID 26546280, 2015). "Given the observational design and close interrelationships of these factors, we are unable to comment on the relative importance of glucose, insulin and insulin resistance for future outcomes." (PMID 25940643, 2015). "Surprisingly, markedly less is known for the more prevalent T2DM, which is mainly characterized by insulin resistance but also insulin secretory defects, resulting in variable insulin levels." (PMID 25742620, 2015). "Studies have already shown that dysregulation of phosphoinositide-3 kinase and mitogen-activated protein kinase pathways lead to defective insulin response and subsequent insulin resistance." (PMID 26202599, 2015). "The fasting glucose, insulin, insulin resistance, and tumor necrosis factor alpha and erythrocyte enzymatic antioxidants were measured." (PMID 25650289, 2015). "In another study, post-natal protein restriction resulted in insulin resistance in male rats while females developed insulin sensitivity in second generation." (PMID 26561832, 2015). "When either the compensatory insulin secretory responses decrease or insulin resistance increases, or when both occur, it results in impaired glucose tolerance." (PMID 26204833, 2015). "Taken together, our research showed that O-GlcNAcylation of PTP1B can influence insulin signal transduction by modulating its own phosphatase activity, which participates in the process of hepatic insulin resistance." (PMID 26402673, 2015).
Insulin resistance (continued). "The GLP-1 belonging to the incretin family activates the proliferation of pancreatic β-cells and increases the secretion of insulin, regulating the glucose and insulin levels and insulin resistance." (PMID 28031898, 2015). "Both insulin concentration and insulin resistance, expressed as HOMA-IR, were higher in Coca-Cola drinking groups than in water drinking groups, regardless of prenatal intervention." (PMID 25891868, 2015). "Our findings revealed for the first time that BB lowered blood levels of glucose and insulin, concomitant with decreased blood triglyceride and lipid profiles, and ameliorated insulin resistance and dyslipidemia in mice on HFD." (PMID 26492243, 2015). "Because fasting insulin levels can also indicate insulin resistance to some extent as HOMA-IR does, it was negatively correlated with mtDNAn (−0.015, p < 0.05)." (PMID 26110043, 2015). "Skeletal muscle insulin resistance is a common defect in type 2 diabetes because nearly 90% of the insulin mediated glucose is taken up by skeletal muscle." (PMID 25889508, 2015). "A previous study in mice infused with insulin suggested that basal hyperinsulinemia also leads to generalized insulin resistance." (PMID 26627187, 2015). "Increased plasma levels of insulin and leptin denoted insulin resistance and leptin resistance in HF-DIO mice." (PMID 26633898, 2015). "The most recent result of OGTT in this patient showed hypersecretion of insulin and delayed response, which is a pattern of insulin resistance largely attributable to excessive recovery from malnutrition (i.e., the so-called tendency of metabolic syndrome)." (PMID 26233654, 2015). "Kupffer cells are thought to contribute to insulin resistance by the production of proinflammatory cytokines that inhibit insulin signaling in hepatocytes." (PMID 25815343, 2015). "Another GWAS that examined fasting insulin and insulin resistance from the HOMA model in 1497 African American and West African subjects identified two novel loci at SC4MOL and TCERG1L [40•]." (PMID 26285759, 2015). "Phenotypic characterization revealed that the TSOD mouse had both insulin resistance and impaired glucose-stimulated insulin secretion." (PMID 25889885, 2015). "Recent evidence shows that it is also associated with metabolic disorders and other components of metabolic syndrome (MS) such as hypertension (HTN), dyslipidemia, glucose intolerance, obesity, insulin resistance and reduced insulin secretion." (PMID 25886602, 2015). "While recent studies suggested that TNF-a enhanced the insulin resistance in infection by inhibiting insulin-induced tyrosine phosphorylation of insulin receptor substrate-1(IRS-1)." (PMID 26137892, 2015). "First, BMI percentile was positively correlated with insulin resistance (fasting insulin and HOMA-IR), lipid profiles (LDL-c, TG and TC), and inflammatory markers (hs-CRP, MCP-1, TNF-α, PAI-1, and leptin) but negatively correlated with adiponectin level." (PMID 26011530, 2015). "Plasma insulin concentration and insulin resistance (HOMA-IR) was significantly reduced in treated groups compared with the diabetic control group." (PMID 26699937, 2015). "High concentrations of FFA induced insulin resistance and impaired the insulin producing function of pancreatic β-cells." (PMID 26080706, 2015). "Adrenal epinephrine released during sympathetic activation triggers glucose production and impairs insulin secretion, thereby promoting insulin resistance." (PMID 25834642, 2015). "IRS-1 plays a pivotal point in the switch to insulin resistance, where serine phosphorylation of IRS-1 causes a conformational change in the IRS-1, preventing insulin induced tyrosine phosphorylation." (PMID 26400768, 2015). "Here, we present in vivo and ex vivo data providing evidence that increased circulating levels of insulin trigger fatty liver development and insulin resistance by stimulating hepatic expression of the FA transporter Cd36 in a Pparγ-dependent manner." (PMID 26085100, 2015).
Insulin resistance (continued). "Hepatic insulin resistance, characterized by reduced sensitivity to insulin's suppression of endogenous glucose production, only occurs in obese PCOS women." (PMID 26124830, 2015). "In recent years, most research efforts have been focused primarily on studying adipocytes, secreting insulin-sensitizing adipokines, which play a pivotal role in the peripheral insulin resistance and the development of MetS." (PMID 25945347, 2015). "A concurrent correlation analysis showed that body mass index (BMI) percentile and fasting insulin were positively correlated with insulin resistance, lipid profiles, and inflammatory markers but negatively correlated with adiponectin." (PMID 26011530, 2015). "The results of the present study showed that exposure to the HFD resulted in metabolic dysfunction as reflected by significant weight gain, fat mass gain, increased fasting insulin levels and insulin resistance." (PMID 26448649, 2015). "IGT is substantially associated with insulin resistance, whereas impaired fasting glucose (IFG) is related to impaired insulin secretion." (PMID 26347060, 2015). "To investigate the molecular link between inflammatory stress and insulin resistance, we investigated the role of the mTOR/S6K pathway on insulin signaling." (PMID 26449763, 2015). "Tacrolimus can reduce insulin secretion, increase islet apoptosis, and exacerbate insulin resistance." (PMID 25721247, 2015). "The combination of prenatal diesel exposure and adult high fat diet increased serum insulin, insulin resistance, and IL-1b, again only in male mice." (PMID 27099868, 2015). "Increasing evidence implicates skeletal muscle as a major contributor to the development of insulin resistance since muscle is the most abundant insulin-sensitive tissue in the body." (PMID 25789156, 2015). "Corroborating the enhanced insulin action in mice treated with the combination therapy, the homeostasis model assessment of insulin resistance (HOMA-IR) showed improved insulin sensitivity only in mice treated with the combination therapy (Fig4G)." (PMID 25652173, 2015). "C. caudatus supplementation significantly improves insulin resistance and insulin sensitivity in patients with type 2 diabetes." (PMID 26713097, 2015). "The insulin resistance index calculated by the HOMA model (HOMA-IR) using level of fasting insulin (μIU/mL) and glucose level (mmol/L) indicated that OVX control, diabetic, and OVX diabetic groups exhibited higher HOMA-IR values when compared to sham group." (PMID 25834745, 2015). "So, insulin resistance in ECs, which is a dysfunction characterized by the impairment of insulin signaling, is considered to lead to the initiation and progression of vascular and vascular-related diseases." (PMID 26338710, 2015). "As a consequence, mice that lacks BBS proteins exhibit hyperglycemia, insulin resistance and blunted insulin-induced activation of IR signaling in insulin sensitive tissues (liver, skeletal muscle and adipose tissue)." (PMID 26103456, 2015). "In the present study we found a significant decrease in fasting plasma insulin concentration and insulin resistance in the experimental group." (PMID 26593941, 2015). "Bitter melon supplementation improved insulin resistance and lowered serum insulin and leptin to the high fat diet fed rats." (PMID 25650336, 2015). "Since Akt is a critical node in regulating insulin and growth factor biological actions, our findings contribute to identify Nck1 as a potential target in therapeutic strategies for insulin resistance and cancer." (PMID 25398386, 2014). "There is evidence of decrease in the insulin-stimulated NO production by the endothelial and smooth muscle cells in the presence of insulin resistance." (PMID 25601838, 2014). "Skeletal muscle is the major tissue responsible for insulin-stimulated glucose disposal and therefore considered as a primary target in the onset of insulin resistance." (PMID 25058613, 2014).